APC2 (APC regulator of Wnt signaling pathway 2)
Diseases named in the same sentence as APC2 in open-access papers (continued):
Sharing a sentence is not in itself a finding about the gene and the disease.
colitis (1 paper, 2015). Inflammation of the colon. "Aberrant methylation of APC2 (adenomatousis polyposis coli 2), SFRP1 (secreted frizzled-related protein 1), and SFRP2 (secreted frizzled-related protein 2) is associated with the progression from colitis to neoplasia." (PMID 26101583, 2015).
colorectal adenocarcinoma (1 paper, 2018). The most common type of colorectal carcinoma. "The mRNA expression of APC2 was found to be significantly downregulated in colorectal adenocarcinoma compared to normal tissues (fold change ≥ 2, p < 0.0001)." (PMID 30510602, 2018).
Intellectual disability (1 paper, 2025). "Loss of the destruction complex member, APC2, leads to lissencephaly, characterized by intellectual disability and neuromotor impairments." (PMID 40377402, 2025). "In Apc2 null mice, disrupted neuronal migration results in defects in the lamination of the cerebral cortex and cerebellum, which manifest as lissencephaly, characterized by a smooth brain surface, severe intellectual disability, seizures, and motor dysfunction." (PMID 40377402, 2025).
Lissencephaly (1 paper, 2025). A spectrum of malformations of cortical development caused by insufficient neuronal migration that subsumes the terms agyria, pachygyria and subcortical band heterotopia. "Hence, the loss of APC2 implicates increased Wnt/β-catenin in lissencephaly." (PMID 40377402, 2025).
lymph node metastasis (1 paper, 2020). "The chi-square analysis showed that low APC2 expression was associated with lymphovascular invasion, lymph node metastasis, and TNM stage of CRC, indicating that low expression of APC2 was prevalent in patients who underwent late clinical analyses." (PMID 32951505, 2020). "APC2 was associated with lymphovascular invasion, lymph node metastasis, and TNM staging." (PMID 32951505, 2020). "Furthermore, ROC curves confirmed that APC2 was associated with lymphovascular invasion (P = 0.004), lymph node metastasis (P = 0.002), and TNM staging (P = 0.002)." (PMID 32951505, 2020).
lymphocytic leukemia (1 paper, 2018). "Hypermethylation of the APC2 gene was also reported in a large-scale methylation analysis of lymphocytic leukemia." (PMID 30510602, 2018).
meningioma (1 paper, 2012). A generally slow growing tumor attached to the dura mater. "Regarding downstream gene cascades of Akt, apoptosis-induced genes including CASP9 (3.78-fold), CDKN1A (8.64-fold), AXIN2 (2.78-fold), APC2 (3.12-fold), and EP300 (5.35-fold) were detected with significant down-regulation in fibroblastic meningiomas." (PMID 23285163, 2012).
non-insulin dependent diabetes mellitus (1 paper, 2015). "Interestingly, APC2 as another partner protein of SPARC was strikingly up-regulated in the STZ-induced diabetic pancreas." (PMID 26110898, 2015).
oral cancer (1 paper, 2015). "Overexpression of pro-inflammatory chemokines, hypomethylation of PTGS2, and hypermethylation of APC2 may be causally linked to the etiology of oral cancer in this model." (PMID 25635769, 2015). "Overexpression of pro-inflammatory chemokines, hypomethylation and overexpression of PTGS2, and hypermethylation and underexpression of APC2 may all be causally linked to the etiology of oral cancer in this model." (PMID 25635769, 2015).
ulcerative colitis (1 paper, 2025). An inflammatory bowel disease involving the mucosal surface of the large intestine and rectum. "In ulcerative colitis, inflammation is thought to be associated with both increased APC2 methylation and decreased expression findings due to decreased SFRP4 methylation in non-inflamed areas." (PMID 40521787, 2025). "In this study, the methylation and expression status of SFRP2, SFRP4, SFRP5, APC1, and APC2 genes were evaluated for the first time in ulcerative colitis patients in the Turkish population." (PMID 40521787, 2025).
uterine corpus endometrial carcinoma (1 paper, 2022). A endometrial carcinoma (disease) that involves the body of uterus. "In uterine corpus endometrial carcinoma, higher expression of miR-6511b-5p is associated with an increased risk of death and recurrence by regulating APC2." (PMID 35590122, 2022).
tumor (42 papers, 2009 to 2025). "Tumour incidence was assessed in aged APC2-deficient mice, which also carried a hypomorphic Apc allele." (PMID 31291912, 2019). "Comparison of expression levels demonstrated higher levels of both Wif1 and Axin2 within APC2-deficient tumours c,d." (PMID 31291912, 2019). "Estrogen receptor alpha (ERα) also showed differential staining between APC2-deficient tumours compared to the APC2-proficient tumour analysed." (PMID 31291912, 2019). "Our study also indicated that low APC2 expression in patients with CRC was associated with poor tumor prognosis, suggesting that APC2 could be a useful diagnostic and prognostic marker for CRC patients." (PMID 32951505, 2020). "It is thus possible to hypothesize that, similar to previously published models, deleting Pten in granulosa cells of APC2-deficient ovaries would lead to rapid tumour development." (PMID 31291912, 2019). "Multiple tumor-associated genes including HP1α, APC2 are differentially expressed; and signaling pathways involved in cellular growth, adhesion, angiogenesis, hypoxia, apoptosis, and canonical Wnt signaling pathways are significantly altered in A549, H1299, and H1975 cells upon G9a knockdown." (PMID 30348169, 2018). "In addition, the ROC curve revealed that APC2 may have potential diagnostic value with respect to distinguishing tumor lymphatic invasion, lymph node metastasis, and TNM staging." (PMID 32951505, 2020). "A study reported on the tumor suppressive function of APC-2 gene in both Rb tumor samples and Y79 cells." (PMID 38929279, 2024). "Of note, another report found reduced Wnt activity following EHMT2 perturbation, in three cell tumor cell lines; A549, H1299, and H1975 which invokes an APC2-mediated mechanism, albeit in a distinct cellular context from what we describe." (PMID 35983994, 2022). "These regions contained tumor-related genes, such as Muc16, Pik3, and Bcl2 in amplification regions and Hras, Notch1, Apc2, Ccnd1, Batf2, Dapk3, Smarca4, Traf2, Traf3, Cdk3, and Cdh4 in deletion regions." (PMID 36424557, 2022). "The tissue microarray test results in 139 patients with CRC indicated that both FOXO4 and APC2 were downregulated significantly in CRC tumor lesions than normal tissue adjacent to carcinoma." (PMID 34631691, 2021). "Module-1 of the ENDCAP-C study showed that their panel of five markers (SFRP2, SFRP4, WIF1, APC1A, and APC2) was accurate in detecting pre-cancerous and invasive neoplasia and dysplasia." (PMID 34842672, 2021). "Both FOXO4 and APC2 were expressed in normal tissues adjacent to carcinoma but less in tumor lesions." (PMID 34631691, 2021). "CRC patients with low APC2 expression exhibited obvious lymphovascular invasion (P = 0.010), lymph node metastasis (P = 0.007), and high tumor node metastasis (TNM) stage (P = 0.007)." (PMID 32951505, 2020). "The tumour suppressor role of APC2 protein in ovarian granulosa cell tumour formation has been highlighted here for the first time and the current study provides further evidence of the roles of WNT signalling activation in the pathogenesis of ovarian GCT." (PMID 31291912, 2019). "In general, the expression patterns of most of the markers examined was similar in the Apc2+/+, Apc2+/− and Apc2−/− tumours." (PMID 31291912, 2019). "Another important caveat to this study was the small numbers of aged Apc2−/− mice available for tumour development studies." (PMID 31291912, 2019). "APC2 was significantly hypermethylated in tumor compared to adjacent tissues (43.93% vs 7.31%, p < 0.05)." (PMID 30510602, 2018). "Methylation analysis of APC2 in tumor (n = 66) and corresponding adjacent formalin-fixed and paraffin-embedded (FFPE) tissues (n = 44) was performed by Sequenom EpiTYPER® and verified by cloning-based bisulfite sequencing analysis." (PMID 30510602, 2018). "Adenomatous polyposis coli 2 (APC2) is a tumor suppressor and is expressed in different tissues and cell lines." (PMID 28661420, 2017).
tumor (continued). "Concordantly hypermethylated CpGs were associated with genes involved in Cadherin, Wnt and Notch signaling pathways, many of which have been previously reported as frequently methylated in a variety of neoplasms, such as APC2, SFRP2, CDH13, CDH15 and PCDH10." (PMID 22737091, 2012). "Only the APC2 and EVL genes displayed higher methylation in the normal progression of a tumor from well to moderate to poor differentiation, with the APC2 gene showing 91%, 97%, and 100% and the EVL gene showing 75%, 77%, and 100%, respectively." (PMID 19750230, 2009). "In a study investigating prognostic factors in CRC, He et al15 reported that APC2 is hypermethylated and may serve as a biomarker of tumor formation in Chinese CRC patients." (PMID 40521787, 2025). "However, the regulatory factors reported in these studies are inconsistent, and downstream targets of PRPF8, such as PIRH2, RBMX, and APC2, exhibit low reproducibility across different tumor types." (PMID 40136404, 2025). "Furthermore, mutations in the APC2 gene, which are directly linked to APC’s tumor-suppressive function, are also associated with worse prognosis in CRC patients." (PMID 37835512, 2023). "Similarly, APC2 mutations, which are directly associated with APC’s tumor-suppressive function, have been linked to worse prognosis in CRC patients." (PMID 37835512, 2023). "Our model is based on the induction of mutant clones in the Wnt pathway (Apc and Apc2) in the adult fly intestine, and the overexpression of the oncogenic form of Ras, RasV12, facilitating the generation of tumor-like overgrowths similar to those found in human CRC tumors." (PMID 37446068, 2023). "In addition, circ-PKD2 weakened the tumor-promoting effects of miR-204-3p-driven APC2 on OSCC development through various signaling pathways." (PMID 32041942, 2020). "Interestingly, miR-939 has been suggested to function as a tumor promotor by regulating Wnt signaling through direct suppression of the previously discussed APC2 tumor suppressor." (PMID 31614568, 2019). "Due to limitation of available tumour samples, qRT-PCR analysis could only be performed on two WNT signalling target genes (Wif1 and Axin2) using RNA from two Apc2-deficient GCTs, with Apc2-proficient ovaries used as control material." (PMID 31291912, 2019). "Furthermore, APC2 has been found to be hypermethylated in both RB tumor samples and the Y79 cell line, mediating the reduction of β-catenin levels." (PMID 30510602, 2018). "APC2 is a tumor suppressor and a negative regulator of Wnt signaling." (PMID 28661420, 2017). "The tumor suppressor APC2 was found to be the major target of miR-3648 in ER stressed cells." (PMID 28661420, 2017). "Moreover, Adenomatous polyposis coli 2 (APC2), a tumor suppressor and a negative regulator of Wnt signaling, was found to be the direct target of miR-3648." (PMID 28661420, 2017). "APC2 is a well-known tumor suppressor, mainly due to its suppressive role in the Wnt signaling." (PMID 28661420, 2017). "APC2 stage-dependent methylation from stage I to stage IV (82% to 97%) was also observed and this may be consistent with the tumor suppressor activity of APC2 gene in CRC and its link to the Wnt pathway." (PMID 19750230, 2009). "This likely explains the lack of pAKT staining in the APC2-deficient tumours." (PMID 31291912, 2019). "To further verify the role of FOXO4 and APC2 in tumor invasion and metastasis in vivo, we injected four groups of SW620 cells (normal, OE-FOXO4, sh-APC2, OE-FOXO4 + sh-APC2) into the spleen and liver of nude mice, respectively." (PMID 34631691, 2021). "Although the tumor suppressive effect of APC has been established in a wide range of tumors, the function of APC2 has only been recognized in a limited number of tumors." (PMID 32951505, 2020). "In the stage 2 analysis, five markers accurately discriminated between neoplasia and control samples with p < 0.0001 – SFRP2, SFRP4, WIF1, APC1A and APC2; with between 40% and 76% increases in geometric mean values." (PMID 30473377, 2019).
tumor (continued). "Marker expression patterns in tumours derived from 12 to 18 month Apc2+/− and Apc2−/− mice were compared with the single GCT which formed in an 18 month Apc2+/+ animal (all animals also carrying the hypomorphic Apc allele )." (PMID 31291912, 2019). "However, the lack of both pAKT and PTEN staining in the Apc2+/+ tumour may result from the hypomorphic APC allele on its own being an insufficiently strong driver of WNT signalling to activate PI3K/AKT signalling via established cross-talk mechanisms." (PMID 31291912, 2019). "Bcl2, VEGFA, PTEN, Jun, Fos, APC2 were up-regulated and Ccna2, Cdc25a, Mcm3, Mcm6, Ccnb2, Mcm5, Cdk1, Gadd45a, Myc were down-regulated in MMQ tumor stem-like cells group." (PMID 28163656, 2017). "In pathway in cancer and cell cycle, Bcl2, VEGFA, PTEN, Jun, Fos, APC2 were up-regulated and Ccna2, Cdc25a, Mcm3, Mcm6, Ccnb2, Mcm5, Cdk1, Gadd45a, Myc were down-regulated in the MMQ tumor stem-like cells." (PMID 28163656, 2017). "Similarly, few tumor tissues were observed in the liver of the OE-FOXO4 group, but the sh-APC2 group had the most tumor tissues, followed by the standard and sh-APC2 groups." (PMID 34631691, 2021). "Furthermore, Apc2+/− and Apc2−/− GCTs showed strong PTEN staining, in contrast to no staining in the Apc2+/+ tumour." (PMID 31291912, 2019).
cancer (25 papers, 2013 to 2026). A tumor composed of atypical neoplastic, often pleomorphic cells that invade other tissues. "APC2 mRNA expression was also investigated in different types of cancer and decreased levels were associated with cancer progression." (PMID 29743633, 2018). "Although APC2 expression is significantly decreased in CRC samples and associated with CRC patients, More work on APC2 for human cancers is needed." (PMID 34000297, 2021). "Silencing APC2 attenuates the inhibitory effects on cell proliferation and the Wnt signaling pathway in cancer cells, in which G9a is silenced or suppressed." (PMID 32951505, 2020). "Restoring HP1α and silencing APC2 respectively attenuated the inhibitory effects on cell proliferation and Wnt signaling pathway in cancer cells in which G9a was silenced or suppressed." (PMID 30348169, 2018). "To explore how G9a inhibition upregulated APC2 gene expression, we examined the promoter methylation changes of APC2 in A549, H1299, and H1975 cancer cells treated with UNC0638." (PMID 30348169, 2018). "Several studies have been carried out to explore the molecular mechanism of APC2 in cancers, and which imply that APC2 plays an important role in tumorigenesis and cancer development." (PMID 30510602, 2018). "In addition, loss of APC and APC2 results in increased expression of the Wnt signaling target genes cMYC and Sox9, lending further weight to the clinical relevance of the loss of both genes, especially for a difficult to treat sub-population of human cancer patients." (PMID 27694902, 2017). "CARP-1 functional mimetics (CFMs) are a novel class of small molecule compounds that interfere with CARP-1 binding with APC/C subunit APC-2, and suppress growth of a variety of cancer cells in part by promoting apoptosis." (PMID 23826121, 2013). "First, we analyzed the expression of APC2 mRNA in different cancer tissues using the Gene Expression Profiling Interactive Analysis database and revealed that APC2 expression was generally downregulated in most cancer tissues." (PMID 32951505, 2020). "UCSC Cancer Browser analysis revealed three H3K27me3 binding sites within the APC2 promoter." (PMID 31367244, 2019). "This was confirmed by our analysis since all candidate CNVs that we have identified and that were found to affect the cancer genes PMS2, APC2, POU5F1, KANSL1, DOCK8 and TMTC3 are part of this category." (PMID 33503040, 2021). "Western blot analysis confirmed that UNC0638 treatment dramatically reduced the level of H3K9Me2, increased the levels of APC2, DKK1, and WIF1 proteins, and resulted in decreased β-catenin in these cancer cells." (PMID 30348169, 2018). "In pathway in cancer, we found that Bcl2, VEGFA, PTEN, Jun, Fos, APC2 gene expression were up-regulated and the expression of Myc was down-regulated in the MMQ TSLCs." (PMID 28163656, 2017). "However, it is conceivable that the loss of APC renders these cancers dependent on APC2, and to our knowledge this hypothesis has not been tested." (PMID 24806839, 2014). "MYC, CDKN2A, PTEN, HARS, APC2, and APC are often referred to as miRNAs in cancer." (PMID 33959508, 2021). "Moreover, in contrast to the other catalytic core subunit APC2, which was shown to be down-regulated in various cancer types, APC11 expression has never been investigated previously in cancer." (PMID 29743633, 2018).
colorectal (1 paper, 2018). "APC2 has been shown to be hypermethylated in more than 90% of CRC tumors, indicating that downregulation of expression of APC2 is likely to be an important step in colorectal tumorigenesis." (PMID 29027285, 2018).
APC2 also shares sentences with these, for which no sentence is quoted: glioblastoma (2 papers); melanoma (2); non-small cell lung carcinoma (2); allergic asthma (1); amyloidosis (1); amyotrophic lateral sclerosis (1); Angelman syndrome (1); autism (1); autism spectrum disorder (1); basal cell carcinoma (1); colorectal tumours (1); dysgerminoma (1); epilepsy (1); familial restrictive cardiomyopathy-6 (1); germ cell tumor (1); germinoma (1); heart defects (1); Hyperkeratosis (1); Hypertension (1); infection (1); invasive ductal carcinomas (1); leukemia (1); lung adenocarcinoma (1); Meckel-Gruber syndrome (1); medulloblastoma (1); neurodevelopmental disorder (1); non-alcoholic fatty liver disease (1); Oral Squamous Cell Carcinomas (1); osteosarcoma (1); ovarian failure (1).
A further 6 diseases each share a sentence with APC2 in 1 paper.